GALNTL6 (polypeptide N-acetylgalactosaminyltransferase like 6)
Description:
Catalyzes the initial reaction in O-linked oligosaccharide biosynthesis, the transfer of an N-acetyl-D-galactosamine residue to a serine or threonine residue on the protein receptor.
Synonyms: GALNT17; GalNAc-T6L; GALNACT20
Tractability: Antibody: UniProt predicts a signal peptide or a membrane-spanning region.
Gene: Protein-coding gene on chromosome 4 (171,812,254 to 173,041,559, forward strand). Ensembl gene ENSG00000174473.
Subcellular location: Golgi apparatus membrane
Pathways (Reactome):
Metabolism of proteins: O-linked glycosylation of mucins
Gene Ontology:
Molecular function: polypeptide N-acetylgalactosaminyltransferase activity
Biological process: protein O-linked glycosylation via N-acetyl-galactosamine; protein O-linked glycosylation
Cellular component: Golgi apparatus; Golgi membrane
Genetic constraint (gnomAD): Loss-of-function variants: 29 observed, 50.88 expected, observed/expected ratio (o/e) 0.57, 90% interval 0.42 to 0.78. The upper end of that interval is the gene's LOEUF score, 0.78, which puts it in group 3 of 6, group 1 being the genes least tolerant of losing a copy. Missense variants: 466 observed, 590.38 expected, observed/expected ratio (o/e) 0.79, 90% interval 0.73 to 0.85. Synonymous variants: 204 observed, 217.54 expected, observed/expected ratio (o/e) 0.94, 90% interval 0.84 to 1.05.
Homologues: Orthologues: chimpanzee GALNTL6 (99% identical), macaque GALNTL6 (99% identical), dog GALNTL6 (98% identical), pig GALNTL6 (98% identical), rabbit GALNTL6 (97% identical), guinea pig GALNTL6 (97% identical), mouse Galntl6 (96% identical), rat Galntl6 (96% identical), tropical clawed frog galntl6 (88% identical), zebrafish galntl6 (82% identical), Drosophila melanogaster Pgant6 (42% identical), Caenorhabditis elegans gly-10 (41% identical), and 11 more. Paralogues in human: GALNT10 (72% identical), GALNT1 (39% identical), GALNT13 (39% identical), GALNT5 (36% identical), GALNT7 (35% identical), GALNT6 (35% identical), GALNT4 (34% identical), GALNT11 (34% identical), GALNT12 (33% identical), GALNT3 (33% identical), GALNT16 (33% identical), GALNT14 (32% identical), and 7 more.
Diseases named in the same sentence as GALNTL6 in open-access papers:
GALNTL6 is named in the same sentence as 14 diseases in open-access papers, as found by Europe PMC text mining. Sharing a sentence is not in itself a finding about the gene and the disease. The quoted sentences say what the papers report.
thyroid cancer (3 papers, 2022 to 2023). "Among the poor prognosis-related genes, TRABD2B (also known as TIKI2), IL17F, and GALNTL6 were reported to be related to the oncogenesis of renal cell carcinoma, cutaneous T-cell lymphoma, and thyroid carcinoma, respectively." (PMID 36816541, 2023). "The role of the up-regulation of GALNTL6 in thyroid cancer is still unknown and is worthy of investigation." (PMID 35267472, 2022). "Several hypermethylated genes (GALNTL6, HTR7, SPOCD1, CDH16 and GRM5) related to thyroid cancer have been discovered to be up-regulated in our study, as were investigated in other reports to mentioned in the following text." (PMID 35267472, 2022).
Hypertension (2 papers, 2020 to 2021). The presence of chronic increased pressure in the systemic arterial system. "GALNTL6 has been associated with lipid metabolism, body mass index, and hypertension." (PMID 32400971, 2020).
clear cell renal carcinoma (1 paper, 2022). A malignant epithelial neoplasm of the kidney characterized by the presence of lipid-containing clear cells within a vascular network. "The finding that LAMA4, BIRC7, GALNTL6, WNK2, and IGFBP2 are potential targets of miR-217 at different times of tumor evolution may help to develop stage-specific strategies, taking into account the differential expression of miR-217 in each stage of clear cell renal carcinoma progression." (PMID 35936681, 2022).
gastric cancer (1 paper, 2024). A primary or metastatic malignant neoplasm involving the stomach. "The clinical weight of this unique lncRNA was first reported in hepatocellular carcinoma and gastric cancer patients with low-expressed linc-GALNTL6-4, which indicated the worst prognosis and survival rates." (PMID 39362599, 2024).
Obesity (1 paper, 2024). Accumulation of substantial excess body fat. "We employed transcriptomic analysis of public dataset GSE199063, and cross validations in two large transversal cohorts to report evidence of a previously unknown association of adipose linc-GALNTL6-4 with obesity." (PMID 39362599, 2024). "•Impaired adipocyte-specific linc-GALNTL6-4 levels are mainly due to the inflammatory state in the context of obesity." (PMID 39362599, 2024). "In fat cells, linc-GALNTL6-4 may preserve adipocyte function, and thus be of use as a therapeutic candidate in the field of obesity and related diseases." (PMID 39362599, 2024). "Accordingly, the scrutiny of linc-GALNTL6-4 dynamics in adipose biopsies from obese subjects revealed overall decreased levels apparently driven by the inflammatory component of obesity, the levels being restored when this condition was solved upon weight loss." (PMID 39362599, 2024). "To conclude, the observed changes in the adipocyte lipidome upon manipulations of linc-GALNTL6-4 support our notion that this lncRNA acts anti-obesogenic and its reduced expression in obese adipose tissue promotes through multiple mechanisms the metabolic dysregulations characteristic of obesity." (PMID 39362599, 2024). "We queried next the abundance of linc-GALNTL6-4 in SC and omental (OM) fat samples of an independent cohort of individuals with and without obesity (body mass index (BMI) threshold of 30 kg/m2)." (PMID 39362599, 2024).
papillary thyroid carcinomas (1 paper, 2020). "According to previous study, the expression of GALNTL6 was most frequently amplified in genome of papillary thyroid carcinomas." (PMID 32306508, 2020).
cancer (3 papers, 2022 to 2026). A tumor composed of atypical neoplastic, often pleomorphic cells that invade other tissues. "Furthermore, the target genes of miR-217 have a known role in cancer progression—for instance, in stage II network, GALNTL6 is overexpressed, and it is related to cell signaling, survival, and proliferation." (PMID 35936681, 2022). "Notably, the treatments altered the gene expression of several tumorigenic and immunologic mediators, including MSXI, ZRSR2, GALNTL6, IL24, and IL18R1, which may impact cancer cell behavior." (PMID 42158898, 2026). "There are currently no reports regarding the high expression of GALNTL6 in cancers." (PMID 35267472, 2022).
tumor (2 papers, 2011 to 2022). "Interestingly, insertions at different locations in the GALNTL6 gene that encodes N-acetylgalactosaminyltransferase-like 6 were observed in two tumor samples, 2T and 8T." (PMID 21533036, 2011).
GALNTL6 also shares sentences with these, for which no sentence is quoted: colon cancer (1 paper); cutaneous T-cell lymphoma (1); hepatocellular carcinoma (1); neurological disorders (1); Prader-Willi syndrome (1); renal cell carcinoma (1).